MMP1 (matrix metallopeptidase 1)
Diseases named in the same sentence as MMP1 in open-access papers (continued):
Sharing a sentence is not in itself a finding about the gene and the disease.
autoimmune disease (6 papers, 2016 to 2023). A disorder resulting from loss of function or tissue destruction of an organ or multiple organs, arising from humoral or cellular immune responses of the individual to their own tissue constituents. "An effective administration of MMP-1 inhibitors is beginning a new treatment approach in the management of many diseases such as osteoporosis, autoimmune diseases and cancer." (PMID 28496473, 2017). "Since the regulation of MMPs becomes aberrant in immune cells in many human inflammatory and autoimmune diseases, we also evaluated the effect of Smac127 on MMP-1 production." (PMID 26989333, 2016). "The MMP-1 significant contributions to these diverse biological and pathological conditions denote the probable involvement of this metalloproteinase in the pathogenesis of cancer and autoimmune diseases such as rheumatoid arthritis." (PMID 28496473, 2017). "The ability of FICZ to increase MMP1 levels and thus limit inflammation and fibrotic ECM buildup in TED may have implications for a wide range of inflammatory and autoimmune diseases." (PMID 32439897, 2020).
carotid atherosclerosis (6 papers, 2015 to 2023). A thickening and loss of elasticity of the walls of carotid arteries that occur with formation of atherosclerotic plaques. "Elevated levels of MMP-1 have been observed in human carotid atherosclerosis, possibly suggesting a higher risk of carotid artery atherosclerosis in girls with TS." (PMID 30245717, 2018). "Moreover, the levels of MMP-1, -3, and -12 were significantly positively correlated with cardiovascular and cerebrovascular events in patients with carotid atherosclerosis." (PMID 37160529, 2023). "Thus, the levels of MMP-1, -3, -7, -10 and -12 were increased in patients with carotid atherosclerosis." (PMID 37160529, 2023). "Moreover, CCL19 is upregulated in carotid atherosclerosis, and it enables the enhancement of proliferative capacity and MMP-1 expression in vascular smooth muscle cells, thereby contributing to the pro-atherogenic potential." (PMID 35559253, 2022). "Our research group found that Polydatin can decrease carotid intima-media thickness (IMT), plaque integral and reduce the level of plaque stability related serum indexes such as Hs-CRP, MMP-1, and TIMP in patients with carotid atherosclerosis." (PMID 26557864, 2015).
colitis (6 papers, 2009 to 2025). Inflammation of the colon. "Benzo[a]pyrene (BaP) promotes collagen deposition through the NRF2 signaling pathway and exacerbates DSS-induced colitis by enhancing the expression of the pro-fibrotic protein matrix metalloproteinase-1 (MMP-1) in intestinal epithelial cells." (PMID 41155173, 2025). "Upregulation of several secreted MMPs has been reported in the colonic mucosa of dogs with colitis, including MMP-1, MMP-3, and MMP-13, as well as MMP-2 and MMP-9." (PMID 35751094, 2022). "In line with the results of network pharmacology approach, in vivo studies confirmed that FC alleviated DSS-induced colitis, reduced systemic inflammatory response, and diminished the expression of IL-17 signaling pathway mediators, IL-17A, RORγt, and tissue remodeling factors MMP1, MMP3 and MMP9." (PMID 37161415, 2023). "Comprehensive bioinformatics analysis using RRA, WGCNA, and Cytoscape, as well as in vivo validation using a classic mouse model of colitis revealed CXCL1, IL1B, MMP1, and MMP10 as signature genes of active UC." (PMID 35392084, 2022). "The activity of MMP1, 3 and 9 is controlled by tissue inhibitor of metalloproteinase (TIMP-1), the expression of which is also increased in colitis." (PMID 23700416, 2013). "Therefore, we were not able to explore the effects of ASM-inhibition on MMP-1 expression in our murine models of colitis." (PMID 19787068, 2009).
cyst (6 papers, 2016 to 2025). A sac-like closed membranous structure that may be empty or contain fluid or amorphous material. "Following loss of Par complex function in cyst cells, Mmp1 staining was detected in the cytoplasm of cyst cells, although not at the apical tip of the testis." (PMID 30918053, 2019). "The cyst-derived stromal cells exhibited early chromosomal instability and overexpression of MMP1 and PAPPA, supporting their potential role in ovarian carcinogenesis." (PMID 41296178, 2025). "Immunohistochemical staining including factor VIII, podoplanin, endothelial markers (CD31, CD34, ERG avian V‐ets erythroblastosis virus E26 oncogene homolog), FLI1 (“friend leukemia factor”), and matrix metalloproteinase‐1 (MMP-1) can help to identify cAS in the cyst walls." (PMID 35543776, 2023). "Knockdown of Par-complex components resulted in increased expression of both the JNK target gene Mmp1 and the JNK pathway transcriptional reporter Puc-LacZ in cyst cells." (PMID 30918053, 2019). "Transcriptomic profiling further identified upregulation of MMP1, PAPPA, and CXCL chemokines in cyst-derived stromal cells, implicating extracellular matrix remodeling, IGF signaling, and inflammatory crosstalk as potential stromal drivers of ovarian carcinogenesis." (PMID 41296178, 2025).
endometrial cancer (6 papers, 2010 to 2025). Primary or metastatic malignant neoplasm involving the endometrium (mucous membrane that lines the endometrial cavity). "While MMP-1 has been studied in other carcinomas, such as endometrial carcinoma, its role in OC in Egypt remains underexplored." (PMID 40564842, 2025). "The endometrial carcinoma derived cell line Ishikawa was shown to secrete MMP-1, -2 and -9." (PMID 20942921, 2010). "Long non-coding RNA BANCR promotes endometrial cancer cell proliferation and invasion by regulating MMP2 and MMP1 via ERK/MAPK signaling pathway." (PMID 28199978, 2017). "MMP-1 and -7 were expressed in all but chorioncarcinoma cells, whereas MMP-9 and -15 showed the same expression pattern concerning endometrial cancer cell lines." (PMID 20942921, 2010).
Erythema (6 papers, 2013 to 2023). Redness of the skin, caused by hyperemia of the capillaries in the lower layers of the skin. "The dietary intervention decreased the formation of erythema and inhibited the expression of matrix metalloproteinase-1 (MMP1) caused by UV radiation, which is a key regulator in the photoaging process." (PMID 34444753, 2021). "This study demonstrated that H(H2O)m prevented UV-induced erythema and DNA damage in human skin and also inhibited UV-induced MMP-1, COX-2, IL-6 and IL-1β expressions significantly." (PMID 23637886, 2013). "This molecule shows anti-inflammatory and antioxidant proprieties preventing erythema, edema, and skin changes mediated by ultraviolet light B (UVB) by reduction of metalloproteinase-1 (MMP-1) messenger RNA (mRNA) expression in human keratinocytes." (PMID 32351323, 2020). "We observed that the topical application of EK100 ameliorated dorsal skin erythema and hyperplasia in the UVB-irradiated mice; moreover, the effect may occur by reducing the expression of MMP-1, IL-6, iNOS, and NF-κB." (PMID 27626393, 2016). "Also, similar to UV-induced erythema, we found that UV-induced expression of MMP-1, COX-2, IL-6 and IL-1β mRNA were not significantly changed after 30 min or 1 hr treatments of H(H2O)m (data not shown)." (PMID 23637886, 2013).
gingivitis (6 papers, 2015 to 2025). A disorder involving inflammation of the gums; may affect surrounding and supporting structures of the teeth. "Previous studies reported that the mRNA level of MMP-1, but not MMP-8, was increased in inflamed gingiva obtained from patients with severe gingivitis, and that the protein level of MMP-1 in gingival crevicular fluid decreased after phase I periodontal therapy." (PMID 37083725, 2023).
inflammatory bowel disease (6 papers, 2018 to 2025). A spectrum of small and large bowel inflammatory diseases of unknown etiology. "In inflammatory bowel disease, MMP-1 activity is closely associated with myeloperoxidase (MPO) levels." (PMID 35392084, 2022). "Previous research on celiac disease and inflammatory bowel disease had reported similar imbalances, with elevated MMP-1 and MMP-2 and decreased TIMP-1 and -2 levels in the gut." (PMID 40524059, 2025). "Elevated content of MMP-1 in the blood serum in the case of inflammatory bowel disease indicates an increase in the number of cytokines, i.e., proteins that play a key role in the immune response." (PMID 37895400, 2023). "MMP-1 is involved in fatty acid oxidation and its expression is usually up regulated in inflammatory bowel disease." (PMID 30068314, 2018).
joint diseases (6 papers, 2008 to 2023). "As substance P, pERK, and MMP-1 appear to be indicators of microscale Type I collagen degradation, these molecular regulators should be considered in diagnostic and therapeutic advances as facilitators of hyperalgesia in joint diseases that involve pathologic Type I collagen degradation." (PMID 33319791, 2020). "The thesis of increased—stimulated by MMPs—degradation of PGs/GAGs in the course of JIA is confirmed by significantly higher concentrations of MMP-1 and MMP-3 in the blood of patients with active arthropathy, who qualified for ETA therapy." (PMID 36009392, 2022). "MMP-1 and MMP-13 are closely related to cartilage collagen dissolution, which is a key protein hydrolysis event in joint diseases that is essentially irreversible." (PMID 33995548, 2021). "Under the influence of joint disease, many cytokines and collagen turnover biomarkers accumulate in synovial fluid, including COMP, CC-chemokine ligand 5 (CCL5), matrix metalloproteinase-1 (MMP-1), MMP-3 and MMP-18, as well as tumor necrosis factor-alpha (TNF-α), interleukin-6 (IL-6) and IL-8." (PMID 36835530, 2023).
leukemia (6 papers, 2014 to 2026). A malignant (clonal) hematologic disorder, involving hematopoietic stem cells and characterized by the presence of primitive or atypical myeloid or lymphoid cells in the bone marrow and the blood. "Other important genes involved in the linkage between OS and leukemia are matrix metallopeptidase 1 (MMP-1) and endothelin-1 which are expressed in response to Angiotensin II (Ang II)." (PMID 25519934, 2014). "In this context, it has been reported that thymoquinone consumption moderated the levels of IL-6 and subsequently suppressed MMP-1, MMP-3, VEGF, and decreased TIMP-1 in Leukemia." (PMID 36518397, 2022).
metabolic syndrome (6 papers, 2020 to 2025). A cluster of metabolic risk factors for CARDIOVASCULAR DISEASES and TYPE 2 DIABETES MELLITUS. "A scoring model integrating the total metabolic syndrome score, MMP-1, and AST/ALT ratio demonstrated superior diagnostic accuracy for identifying ≥F2 (AUROC 0.88, 95% CI 0.79–0.97) compared to other NITs and MRE, and strong performance for detecting ≥F3 (AUROC 0.95, 95% CI 0.90–1.00)." (PMID 40572790, 2025). "The newly defined “total metabolic syndrome score”, together with MMP-1 level and AST/ALT ratio, can diagnose ≥F2 with a significantly high PPV and also has higher sensitivity and NPV compared to other NITs and MRE kPa." (PMID 40572790, 2025). "While this model requires validation in both internal and external cohorts, our preliminary findings suggest that future approaches incorporating the total metabolic syndrome score and MMP-1 may hold promise for noninvasive fibrosis staging." (PMID 40572790, 2025). "Combining total metabolic syndrome score, MMP-1, and AST/ALT ratio might detect ≥F2 in MASH with higher diagnostic accuracy than other NITs and MRE." (PMID 40572790, 2025). "MMP-1 seems to be involved in the development of adipose tissue, while plasma levels of MMP-2 and MMP-9 are elevated in patients with the metabolic syndrome." (PMID 34512552, 2021). "The total metabolic syndrome score and MMP-1 levels, two variables not currently included in NITs for MASH, have emerged as promising candidates for future approaches, alongside the widely used AST/ALT ratio." (PMID 40572790, 2025). "The aim of this study is to investigate the plasma levels of MMP-1, MMP-2, MMP-3, MMP-9, TIMP-1, TIMP-2 and their ratios in a large variety of study groups including overweight people and obese people with or without metabolic syndrome and non-obese healthy people with total of 479 participants." (PMID 34625635, 2021).
open-angle glaucoma (6 papers, 2010 to 2025). Chronic outflow obstruction of the eye's drainage canals that can lead to increased internal eye pressure and optic nerve damage. "Ussa and co-workers investigated whether the SNPs of the genes encoding MMP1, MMP2, MMP3, MMP9, and MMP17 were related to the response to latanoprost in 124 Spanish patients with open-angle glaucoma." (PMID 39769228, 2024). "Functional gene polymorphisms of these MMPs such as MMP1 −1607 1G/2G (rs1799750), MMP2 −1306 C/T (rs243865), MMP2 −1575 G/A (rs243866), and MMP9 Q279R (rs17576) are thus plausible candidates as risk factors for open angle glaucomas." (PMID 20808730, 2010). "Importantly, in a pharmacogenetic study involving 117 Spanish patients with open-angle glaucoma, 6 subhaplotypes of the MMP1 gene were associated with lack of response to latanoprost, strongly implicating MMP1 in the mechanism of IOP lowering with PGAs." (PMID 36877514, 2023).
Peri-Implantitis (6 papers, 2019 to 2025). An inflammatory process with loss of supporting bone in the tissues surrounding functioning DENTAL IMPLANTS. "As MMP-1 and MMP-8 are mainly responsible for collagen matrix destruction in peri-implantitis, the MMP-1/TIMP-1 and MMP-8/TIMP-1 ratio shifts in favor of MMPs can serve as an indicator of peri-implantitis progression and inefficiency of treatment." (PMID 37232785, 2023). "The complex formed with sIL-6R in peri-implantitis lesions and IL-6 produced from Clys-stimulated HGFs exacerbates the inflammatory response to produce IL-8, IL-6, and pro-MMP-1 and activate the gp130/STAT3 pathway." (PMID 36834667, 2023). "In addition, MMP-1 may be involved in the pathogenesis of peri-implantitis, given its increase in fibroblasts from peri-implantitis and reduced gene expression of tissue inhibitors of matrix metalloproteinases (TIMP-1), which may indicate a loss of attachment around dental implants." (PMID 35163727, 2022).
rectal cancer (6 papers, 2014 to 2022). A primary or metastatic malignant neoplasm that affects the rectum. "In our results, we identified interactions of high animal protein intake on rectal cancer risk with PDGFB and MMP1 genes previously implicated in inflammation-mediated pathologic processes including tumor progression." (PMID 28956832, 2017).
systemic sclerosis (6 papers, 2012 to 2025). A chronic disorder, possibly autoimmune, marked by excessive production of collagen which results in hardening and thickening of body tissues. "Overall, MMP dysregulation in systemic sclerosis reflects a complex imbalance between decreased MMP-1 and MMP-13 (profibrotic suppression) and increased MMP-9, MMP-14, and MMP-7 (proinflammatory activation)." (PMID 41226358, 2025). "It is known that the expression of MMP-1 and TIMP-1 (MMP-1 inhibitor) reduces during the systemic sclerosis progression." (PMID 34258301, 2021). "Yin and colleagues compared MMP-1 expression after UVA1 phototherapy in normal fibroblasts and fibroblasts with systemic scleroderma, and found increased expression in both groups, but higher expression was observed in fibroblasts with systemic scleroderma than in normal fibroblasts." (PMID 23554742, 2012).
tongue squamous cell carcinoma (6 papers, 2019 to 2024). A squamous cell carcinoma that arises from the tongue. "It has been reported in the literature that the expression of MMP1 is increased in tongue squamous cell carcinoma and is associated with the survival and prognosis of patients 37-39." (PMID 38706907, 2024). "They 37 found that knocking down MMP1 can reduce the proliferation and invasion of the tongue squamous cell carcinoma cell line FADU, and also lead to decreased phosphorylated Akt." (PMID 38706907, 2024). "Mice tongue squamous cell carcinoma model induced by 4-nitroquinoline 1-oxide (4NQO) and siRNA-mediated cellular assay in vitro were utilized to evaluate the oncogenic role of MMP1." (PMID 36105241, 2022). "Functional analysis and luciferase reporter gene assays indicated that has-miR-222 inhibits oral tongue squamous cell carcinoma cell invasion by targeting on matrix metalloproteinase 1 (MMP1) and manganese superoxide dismutase 2 (SOD2) mRNAs." (PMID 31929798, 2019). "KEGG enrichment analysis of abnormally expressed genes in the MMP1 differentially expressed group revealed that MMP1 was positively correlated with PD-L1 expression and PD-1 immune checkpoint-related signaling pathways in nine patients with tongue squamous cell carcinoma." (PMID 39629135, 2024). "Furthermore, conjugation with MMP-1 antibodies resulted in a 3.07-fold higher uptake in HSC-3 (human tongue squamous cell carcinoma) cells as compared to L929 (fibroblast) cells, which translated to a 5-fold decrease in cell viability, confirming SCC targeting." (PMID 35010011, 2021). "To investigate whether MAPK family members are involved in the regulation of MMP1 by SPHK1, we performed gene set enrichment analysis (GSEA) of SPHK1 using RNA-seq data from fresh tumor tissues obtained from nine patients with tongue squamous cell carcinoma before immunotherapy." (PMID 39629135, 2024).
uveal melanoma (6 papers, 2021 to 2025). A melanoma derived from melanocytes of the uveal tract. "MMP1 (Matrix Metallopeptidase 1) influenced the progression of uveal melanoma from stage 3 to stage 4 and was correlated with OS and disease-free survival." (PMID 36147494, 2022). "According to the researchers, MMP-1 expression levels could be applied as biomarkers to predict patient survival in uveal melanoma." (PMID 39769318, 2024).
acute coronary syndrome (5 papers, 2007 to 2024). Signs and symptoms related to acute ischemia of the myocardium secondary to coronary artery disease. "MMP1 is also implicated in the regulation of the platelet aggregation that follows plaque disruption which may result in acute coronary syndrome." (PMID 23497408, 2013). "MiRNA126, miRNA21, and both MMP1 and MMP9 are associated with LV and arterial function parameters in patients with acute coronary syndrome." (PMID 39194717, 2024).
aortic stenosis (5 papers, 2011 to 2026). Aortic valve stenosis is a aortic valve disease caused by the incomplete opening of the aortic valve. "In individuals with mild aortic stenosis, there was a significant relationship observed between the left ventricular end-diastolic volume index and MMP-1 levels, which were also linked to left ventricular volume overload and impaired diastolic function." (PMID 40305314, 2025). "Based on the microarray data, we chose three genes known to be mechanosensitive and associated with aortic stenosis: MMP-1, MMP-3, and IL-6." (PMID 21876831, 2011). "The elevated expression of MMP-1, a collagenase that possesses the ability to cleave the intact triple-helix of fibrillar collagen, has been observed in the early stages of aortic stenosis." (PMID 40305314, 2025).